RNU2-23P (RNA, U2 small nuclear 23, pseudogene)
Gene: Small nuclear RNA gene on chromosome 11 (65,147,584 to 65,147,778, forward strand). Ensembl gene ENSG00000222477.
Homologues: Orthologues: chimpanzee U2 (99% identical), macaque U2 (96% identical), dog U2 (84% identical), mouse Gm22423 (77% identical), rabbit U2 (58% identical). Paralogues in human: RNU2-14P (83% identical), U2 (82% identical), RNU2-2 (81% identical), U2 (81% identical), RNU2-64P (81% identical), RNU2-36P (80% identical), RNU2-59P (80% identical), RNU2-4P (79% identical), RNU2-26P (78% identical), RNU2-32P (78% identical), RNU2-3P (78% identical), RNU2-48P (78% identical), and 66 more.